CAMKK2 (calcium/calmodulin dependent protein kinase kinase 2)
Diseases named in the same sentence as CAMKK2 in open-access papers (continued):
Sharing a sentence is not in itself a finding about the gene and the disease.
Glucose intolerance (5 papers, 2012 to 2025). Glucose intolerance (GI) can be defined as dysglycemia that comprises both prediabetes and diabetes. "CaMKK2 prevented high fat diet-induced glucose intolerance by attenuating the inflammatory response in adipose." (PMID 23730258, 2012).
Anxiety (4 papers, 2014 to 2022). Intense feelings of nervousness, tension, or panic often arise in response to interpersonal stresses. "Furthermore, CaMKK2 null mice representing a loss of function model the human behavioural phenotypes, displaying anxiety and manic-like behavioural disturbances." (PMID 26395653, 2015).
behavioral disorders (4 papers, 2015 to 2022). "Our data provide a novel insight into CaMKK2 regulation and its perturbation by a mutation associated with behavioural disorders." (PMID 26395653, 2015). "Altered CAMKK2 activity has been found to be strongly associated with many behavioral disorders." (PMID 34394017, 2021). "Since aberrant CaMKK2 activity is strongly associated with behavioral disorders and several types of cancer, understanding the functional consequences of these mutations offers new insight into disease risk and burden of disease in human populations carrying these variants." (PMID 28230171, 2017). "Since the G87R and R139W mutants exert a dominant-negative effect on CaMKK2 signaling, these mutations could be considered as potential risk markers for these behavioural disorders." (PMID 28230171, 2017).
cardiac hypertrophy (4 papers, 2014 to 2026). "Histone demethylase JMJD1C, an important epigenetic factor, represses the activation of AMPK during cardiac hypertrophy through the reduction of CaMKK2 expression." (PMID 36555778, 2022). "Furthermore, cardiac-specific inhibition of CaMKK2 worsens cardiac hypertrophy induced by transverse aortic binding accompanied by reduced AMPK and PGC-1α levels and mitochondrial biogenesis." (PMID 32699151, 2020). "Thus, the inactivation of CaMKK2 might indirectly result in the development of metabolic dysfunction and cardiac hypertrophy." (PMID 36555778, 2022). "Specifically, we explore how PCAF-mediated acetylation of calcium/calmodulin-dependent protein kinase kinase 2 (CAMKK2) influences AMPK signaling, thereby regulating cardiac hypertrophy and dysfunction under pathological stress." (PMID 42009955, 2026).
liver cancer (4 papers, 2019 to 2024). An epithelial or non-epithelial malignant neoplasm that arises from the liver. "They showed that knockdown of CaMKK2 attenuated liver cancer cell growth in vitro and in vivo." (PMID 38745046, 2024).
lymphoma (4 papers, 2017 to 2022). A malignant (clonal) proliferation of B- lymphocytes or T- lymphocytes which involves the lymph nodes, bone marrow and/or extranodal sites. "As previously reported in breast tumor models, deletion of Camkk2 in the host is also associated with enhanced T cell response toward an antigen expressed in lymphoma cells." (PMID 34712241, 2021). "We next examined the cell types expressing Camkk2 in the tumor microenvironment and spleen of lymphoma-bearing mice by engrafting E.G7-OVA cells into the flank of [Tg(Camkk2-EGFP)C57BL/6J] Camkk2-reporter mice." (PMID 34712241, 2021). "The results of these studies indicated that the acute deletion of Camkk2 in the host cells was sufficient to induce significant inhibition of the lymphoma cells growth." (PMID 34712241, 2021). "Although this pharmacological approach cannot distinguish the intrinsic effect of STO-609 on tumor cells from those on stroma cells, it provides further evidence on the potential translational impact of targeting CaMKK2 to restrain lymphoma growth." (PMID 34712241, 2021). "Lastly, we evaluated the efficacy of STO-609, a small molecule pharmacological CaMKK2 inhibitor, to suppress the growth of EL-4 lymphoma cells." (PMID 34712241, 2021). "We show syngeneic lymphoma cells fail to survive in mice genetically deleted of Camkk2 and this is reversed by adoptive transfer of MDSCs from spleens of tumor-bearing mice." (PMID 34712241, 2021). "We next leveraged the EG7-OVA lymphoma model to determine the ability of WT and Camkk2-/- mice to develop a specific T cell-mediated response toward the OVA antigen, which is selectively expressed by E.G7-OVA lymphoma cells." (PMID 34712241, 2021). "Here, we demonstrated that the failure of lymphoma cells to grow in Camkk2-/- mice is associated with a decreased accumulation of MDSCs, while the adoptive transfer of MDSC is sufficient to restore the ability of tumor cells to grow in CaMKK2 deficient mice." (PMID 34712241, 2021).
non-alcoholic fatty liver disease (4 papers, 2017 to 2022). "Utilizing these data, we show STO-609 treatment to inhibit CaMKK2 function confers protection against non-alcoholic fatty liver disease." (PMID 28924233, 2017). "In addition, CAMKK2 inhibition protects mice from developing metabolic syndrome shown through a decrease in blood glucose and insulin resistance as well as regression of nonalcoholic fatty liver disease (NAFLD)." (PMID 35741020, 2022).
prostate tumors (4 papers, 2016 to 2022). "Further analysis using ChIP has established that CAMKK2 is indeed a direct target of the AR in prostate tumor biopsies from human patients." (PMID 32927797, 2020).
steatosis (4 papers, 2019 to 2024). Increased lipid within the cytoplasm of cells. "These suggest that cilostazol may protect liver from ethanol induced steatosis and apoptosis, two most important causal factors for alcoholic liver injury, by recovering AMPK signaling through LKB1 and CaMKK2 activation." (PMID 30695051, 2019). "In the mechanistic study, we demonstrated that Cdo1 tethered Camkk2 to AMPKα, which promotes the AMPK activation to improve hepatocyte steatosis." (PMID 38110408, 2023).
Huntington disease (3 papers, 2022 to 2024). Huntington disease (HD) is a rare neurodegenerative disorder of the central nervous system characterized by unwanted choreatic movements, behavioral and psychiatric disturbances and dementia. "For some of these, we were able to predict the effect of a differential phosphorylation on their activity: the decreased phosphorylation in Huntington’s disease mice of CAMK2A and CAMKK2 allows for calcium/calmodulin binding." (PMID 36523271, 2022).
medulloblastoma (3 papers, 2016 to 2021). A malignant, invasive embryonal neoplasm arising from the cerebellum. "It was recently reported that inhibition of CAMKK2 blocks migration of medulloblastoma via CAMKI, and CAMKK2 was proposed as a putative target to limit metastasis in this type of brain tumor." (PMID 27171399, 2016).
mental disorder (3 papers, 2020 to 2024). A disease that has its basis in the disruption of mental process. "The current study has enlightened us that a few of the significant mutations are prime candidates in CAMKK2 which could be the fundamental cause of various bipolar and psychiatric disorders." (PMID 33082841, 2020).
metabolic syndrome (3 papers, 2022 to 2024). A cluster of metabolic risk factors for CARDIOVASCULAR DISEASES and TYPE 2 DIABETES MELLITUS. "In addition, CAMKK2 inhibitors may offer patients a “2 for 1” deal by treating not only the cancer directly, but also disease-linked comorbidities like metabolic syndrome." (PMID 35741020, 2022). "Clearly, the observed benefits of CAMKK2 inhibition on systemic metabolism will need to be formally tested in diverse models of ADT-driven metabolic syndrome to provide a more comprehensive evaluation of anti-CAMKK2-mediated efficacy." (PMID 35741020, 2022). "Previous findings reported that inhibition of CAMKK2 could counteract aspects of metabolic syndrome, as well as protect against NAFLD." (PMID 35741020, 2022). "However, we cannot rule out contributions from other factors linked to metabolic syndrome such as leptin, triglycerides, and free fatty acids that were altered by CAMKK2 deficiency at 15 weeks but not 30 weeks." (PMID 35741020, 2022).
osteoarthritis (3 papers, 2023 to 2025). A noninflammatory degenerative joint disease occurring chiefly in older persons, characterized by degeneration of the articular cartilage, hypertrophy of bone at the margins and changes in the synovial membrane. "We highlight Ca2+/calmodulin-dependent protein kinase kinase 2 (CaMKK2), a serine/threonine protein kinase that was recently identified to play a role in murine and human osteoarthritis pathogenesis by coordinating chondrocyte inflammatory responses and apoptosis." (PMID 37849987, 2023).
asthma (2 papers, 2023 to 2024). "Our study was the first to find that upregulated CISD1 and CAMKK2 inhibited ferroptosis and played an important regulatory role in asthma." (PMID 36843917, 2023). "We found CISD1 was significantly upregulated and CAMKK2 was downregulated in both mild to moderate asthma and severe asthma compared to healthy controls." (PMID 36843917, 2023). "Similar results were also obtained in the GSE143303 dataset, CAMKK2 was significantly downregulated in the asthma group, and CISD1 was significantly upregulated in the asthma group (p < 0.05)." (PMID 36843917, 2023). "CISD1 was significantly upregulated and CAMKK2 was downregulated in both mild to moderate asthma and severe asthma compared to healthy controls in the GSE147878 dataset (p < 0.05), which was consistent with the results of this study." (PMID 36843917, 2023). "Therefore, we verified the expression of CISD1 and CAMKK2 in mild/moderate asthma and severe asthma." (PMID 36843917, 2023). "We, therefore, believe that CAMKK2 was upregulated in asthma, which in turn inhibited ferroptosis." (PMID 36843917, 2023). "We found that CAMKK2 was downregulated in asthmatics and upregulated in animal models of asthma." (PMID 36843917, 2023). "Through validation, we found that CAMKK2 and CISD1 expression were upregulated in the asthma group compared to the control group and would inhibit the occurrence of ferroptosis." (PMID 36843917, 2023). "CAMKK2 and CISD1 are key suppressors of iron-induced cell death in asthma." (PMID 38783263, 2024). "We discovered that CAMKK2 and CISD1 were crucial ferroptosis suppressors in asthma." (PMID 36843917, 2023). "Firstly, we did not obtain consistent results for CAMKK2, which was downregulated in asthma patients and upregulated in the OVA mouse model." (PMID 36843917, 2023). "We discovered CAMKK2 and CISD1 were ferroptosis-related key genes for asthma patients, which could provide a reference for immunotherapies and targeted therapies." (PMID 36843917, 2023).
brain tumor (2 papers, 2016 to 2025). "In brain tumor, CaMKK2 was upregulated in neurons and TAMs, and deficiency of CaMKK2 reprogrammed tumor-promoting TAMs to an immunostimulatory phenotype, improving the efficiency of immunotherapy." (PMID 40725182, 2025).
cervical cancer (2 papers, 2016 to 2019). A primary or metastatic malignant neoplasm involving the cervix. "Four characteristic genes, HSPA14, SDHAF2, CAMKK2 and TM9SF1, that can be used as prognostic markers for cervical cancer were selected." (PMID 31744495, 2019).
diabetic cardiomyopathy (2 papers, 2020 to 2022). Diabetic cardiomyopathy is a disorder of the heart muscle in people with diabetes. "In addition, it was also shown that BH4 exerts its beneficial effects in diabetic cardiomyopathy by activating peroxisome proliferator-activated receptor-γ coactivator 1-α (PGC-1α) signaling by interacting with calcium/calmodulin-dependent protein kinase kinase 2 (CaMKK2)." (PMID 36289741, 2022). "This study reports that BH4 activates CaMKK2/PGC-1α; signaling pathway and has a therapeutic effect on diabetic cardiomyopathy." (PMID 32699151, 2020).
diabetic kidney disease (2 papers, 2024 to 2025). Progressive kidney disorder caused by vascular damage to the glomerular capillaries, in patients with diabetes mellitus. "Although CAMKK2 has been implicated in mitochondrial function associated with diabetic nephropathy, its role and underlying mechanisms in IPF remain unclear." (PMID 41053564, 2025).
epilepsy (2 papers, 2016 to 2022). A brain disorder characterized by episodes of abnormally increased neuronal discharge resulting in transient episodes of sensory or motor neurological dysfunction, or psychic dysfunction. "Upregulation of PRKAB1 and CAMKK2 in this study underscored the pivotal role of energy homeostasis in epilepsy." (PMID 36138892, 2022). "The nomogram, using RELA, PRKAB1, TNFRSF1A, CAMKK2, and CPT1B, was next confirmed as a reliable predictive model for epilepsy that would bring patients a net clinical benefit when the threshold probability ranged from 0.1 to 1.0." (PMID 36138892, 2022).
heart failure (2 papers, 2014 to 2022). Inability of the heart to pump blood at an adequate rate to meet tissue metabolic requirements. "This demonstrates that CaMKK2 can exert beneficial effects against pressure-overload-induced heart failure, thereby providing a therapeutic target for treatment of heart failure." (PMID 36555778, 2022).
hypoxic-ischemic encephalopathy (2 papers, 2020 to 2022). "Moreover, a recent study found that, in a rat model of hypoxic-ischemic encephalopathy, rh-chemerin treatment reverses neurological impairments and alleviates neuronal apoptosis partially through the CMKLR1/CAMKK2/AMPK pathway." (PMID 36012305, 2022).
lung adenocarcinoma (2 papers, 2021 to 2022). A carcinoma that arises from the lung and is characterized by the presence of malignant glandular epithelial cells. "In this study, CAMKK2 rs1653586G>T was significantly related with the worse response to pemetrexed and survival outcome in lung adenocarcinoma patients." (PMID 36606188, 2022).
myotonic dystrophy type 1 (2 papers, 2022 to 2025). Steinert disease, also known as myotonic dystrophy type 1, is a muscle disease characterized by myotonia and by multiorgan damage that combines various degrees of muscle weakness, arrhythmia and/or cardiac conduction disorders, cataract, endocrine damage, sleep disorders and baldness. "Furthermore, we demonstrated that aberrant splicing of CAMKK2 is associated with abnormal neurite morphology in myotonic dystrophy type 1 motor neurons." (PMID 35770133, 2022).
non-small cell lung carcinoma (2 papers, 2016). A group of at least three distinct histological types of lung cancer, including non-small cell squamous cell carcinoma, adenocarcinoma, and large cell carcinoma. "On the other hand, CAMKK2 is a versatile activator of signaling pathways and in non-small cell lung cancer its role in AMPK activation was proposed as a mechanism for tumor regression." (PMID 27171399, 2016).
Parkinson disease (2 papers, 2024 to 2026). A progressive degenerative disorder of the central nervous system characterized by loss of dopamine producing neurons in the substantia nigra and the presence of Lewy bodies in the substantia nigra and locus coeruleus. "Postmortem temporal cortex tissues from 74 AD patients, 27 Parkinson’s disease (PD) patients, and 17 CN individuals were analyzed for CAMKK2, TF, and TFRC protein levels by Western blotting." (PMID 39669708, 2024).
alcohol dependence (1 paper, 2026). Physical and psychological dependence on alcohol. "Our integrative analysis identified 10 drug-targetable genes showing significant expression alterations in alcohol dependence (FDR < 0.05), with three genes (CDK5R1, CAMKK2 and NRBP1) demonstrating evidence of shared causal variants through colocalization." (PMID 42025296, 2026).
astrocytic tumor (1 paper, 2016). A glial tumor of the brain or spinal cord showing astrocytic differentiation. "Analysis of an available array dataset revealed a significantly lower mRNA expression of CAMKK2 in infiltrating astrocytic tumors (n = 5, p = 0.01), ependymoma (n = 4, p = 0.002), and oligodendroglioma (n = 5, p = 0.03) compared to normal brain tissue (n = 4)." (PMID 27171399, 2016).
Becker muscular dystrophy (1 paper, 2016). Becker muscular dystrophy (BMD) is a neuromuscular disease characterized by progressive muscle wasting and weakness due to degeneration of skeletal, smooth and cardiac muscle. "We found that CaMKK2 mRNA level increased significantly in patients with DMD but not in patients with Becker muscular dystrophy (BMD), which is the milder form of dystrophinopathy." (PMID 27783047, 2016).
cholangiocarcinoma (1 paper, 2023). A carcinoma that arises from the intrahepatic biliary tree (intrahepatic cholangiocarcinoma) or from the junction, or adjacent to the junction, of the right and left hepatic ducts (hilar cholangiocarcinoma). "Here, we studied that bufalin targeting CAMKK2 promotes mitochondrial dysfunction and inhibits the occurrence and metastasis of intrahepatic cholangiocarcinoma through Wnt/β-catenin signal pathway." (PMID 38082327, 2023).
clear cell renal cell carcinoma (1 paper, 2021). "TRPM3 is highly expressed in clear cell renal cell carcinoma and induces a high level of autophagy by activating the upstream CAMKK2/ULK1 cascade and inhibiting endogenous miR-214 through the CAMKK2/AMPK pathway, ultimately promoting tumor growth." (PMID 34895252, 2021).
Cognitive impairment (1 paper, 2019). Abnormal cognition is characterized by deficits in thinking, reasoning, or remembering. "Among the significantly enriched signaling pathways from KEGG analysis, oxytocin signaling pathway (PATH:04921; Cacng2, Adcy1, Kcnj4, Kcnj9, Adcy8, Pik3cd, Elk1, Adcy4, Camkk2, Cacng7, Nos3, Kcnj2) may play an important role in the sevoflurane-induced cognitive impairment." (PMID 31582589, 2019).
Duchenne muscular dystrophy (1 paper, 2016). Duchenne muscular dystrophy (DMD) is a neuromuscular disease characterized by rapidly progressive muscle weakness and wasting due to degeneration of skeletal, smooth and cardiac muscle. "Here, we found that CaMKK2 expression levels were altered under physiological and pathological conditions including postnatal myogensis, freeze or cardiotoxin-induced muscle regeneration, and Duchenne muscular dystrophy." (PMID 27783047, 2016).
gastric adenocarcinoma (1 paper, 2022). "In this study, we determined the regulatory roles of CAMKK2 through tyrosine phosphorylation in gastric adenocarcinoma (AGS) cells." (PMID 35646067, 2022).
intrahepatic cholangiocarcinoma (1 paper, 2023). A carcinoma that arises from the intrahepatic bile duct epithelium in any site of the intrahepatic biliary tree. "Our results suggest that bufalin targeting CAMKK2 promotes mitochondrial dysfunction and inhibits the proliferation and migration of intrahepatic cholangiocarcinoma through Wnt/β-catenin signal pathway." (PMID 38082327, 2023).
knee osteoarthritis (1 paper, 2024). "CAMKK2 may serve as a potential therapeutic target for preventing or alleviating human OA, offering a new direction for knee osteoarthritis treatment." (PMID 39465698, 2024).
memory impairment (1 paper, 2013). "Thus, altered expression of Camkk2 may contribute to seizure-associated memory impairment." (PMID 24005891, 2013).
myocardial infarction (1 paper, 2022). Gross necrosis of the myocardium, as a result of interruption of the blood supply to the area, as in coronary thrombosis. "Analysis of human blood sample sequencing datasets and mouse myocardial infarction sequencing datasets as well as cardiomyocyte hypoxia experiments indicated that FRGs ALOX5, CAMKK2, KDM6B, LAMP2, PTEN, PTGS2, and ULK1 may be potential biomarkers of AMI." (PMID 36407421, 2022).
nonalcoholic steatohepatitis (1 paper, 2022). "The CAMKK2/AMPKα pathway might serve as a promising target in treatment of lipotoxicity in nonalcoholic steatohepatitis." (PMID 35624663, 2022).
osteosarcoma (1 paper, 2020). A usually aggressive malignant bone-forming mesenchymal neoplasm, predominantly affecting adolescents and young adults. "Interestingly, cells with inhibition of CaMKK2, a newly identified kinase involved in regulating the mechano-sensing signaling cascade in osteosarcoma cells, shared the similar actin network phenotype." (PMID 32222698, 2020).